IL4R (interleukin 4 receptor)
Diseases named in the same sentence as IL4R in open-access papers (continued):
Sharing a sentence is not in itself a finding about the gene and the disease.
Granuloma (10 papers, 2010 to 2025). A compact, organized collection of mature mononuclear phagocytes, which may be but is not necessarily accompanied by accessory features such as necrosis. "The synergistic activation of CSF1R and IL4R pathways in granuloma-associated macrophages likely contributes to the persistence and expansion of these lesions while promoting tissue remodeling and fibrosis, ultimately impacting cardiac function." (PMID 40521183, 2025). "At day 30 post-infection, however, CD4+ T cell-specific IL-4Rα deficient mice and wild-type controls showed evidence of granuloma maturation, as defined by an increased number of mature and sterile granulomas, compared with global IL-4Rα−/− mice." (PMID 31475014, 2019). "In fact, B cell deficient mice developed granulomas that were almost twice the size of those from littermate IL-4Rα−/lox mice confirming a central role for B cells in the control of the host granulomatous response during schistosomiasis." (PMID 30619289, 2018). "We found that B cell-specific IL-4Rα-deficient mice had significantly larger granulomas at both 16 and 24 weeks post-infection compared to littermate control mice, suggesting that IL-4Rα expressing B cells are required to downregulate granulomatous pathology during chronic schistosomiasis." (PMID 30619289, 2018). "The concurrent expression of Acetyl-H3K9, Chi3l1, CSF1R, IL4R, TGFß, and Jak3/Stat6 in granulomas of cardiac sarcoidosis promotes the polarization of macrophages toward the M2 phenotype, facilitating anti-inflammatory conditions and driving fibrotic processes." (PMID 40521183, 2025). "The concurrent expression of Acetyl-H3K9, Chi3l1, CSF1R, IL4R, TGFß, and Jak3/Stat6 in granulomas of CS further reinforces macrophages towards M2 polarization, thereby leading to anti-inflammatory states and fibrosis." (PMID 40521183, 2025). "We noted that Sm infection resulted in enlarged egg-driven granulomas in the liver of Foxp3cre IL-4Rα−/lox mice when compared to granulomas in the liver of their littermate control." (PMID 30379806, 2018). "This IL-4Rα-independent MMR+Ym1+ subpopulation was restricted at the periphery of LysMcreIl4ra−/lox granulomas, in contrast to Il4ra−/lox control mice where those cells were in close proximity to the parasite eggs." (PMID 20502521, 2010). "At 119 dpi an increased number of granuloma was observed in the IL-4R−/−/IL-5−/− mice, which hampered the exact worm counts and may explain the lower worm numbers in comparison to the dblGATA and IL-5−/− mice." (PMID 31109364, 2019). "Together, we here introduce an experimental TB model that displays many features of centrally necrotizing granulomas in human post-primary TB and demonstrate that IL-13/IL-4Rα-dependent mechanisms leading to arginase-1 expression are involved in TB-associated tissue pathology." (PMID 24979482, 2014). "Infection of macrophage/neutrophil-specific (LysMcreIl4ra−/lox) and T cell-specific (iLckcreIl4ra−/lox) IL-4Rα-deficient mice showed these mice to have high mortality during acute schistosomiasis irrespective of granuloma formation." (PMID 20502521, 2010). "Our upstream pathway analysis of CSF1R identified IL4R as a regulated gene, corroborating the literature linking interleukin-4 receptor alpha (IL4RA) and interleukin-13 receptor alpha 1 (IL13RA1) signaling to granuloma." (PMID 40521183, 2025). "The absence of these cytokines, or the inability to signal via the IL-4Rα in BALB/c mice, results in a reduced IFN-γ response, severely limited granuloma development, enhanced IL-10 production and disease exacerbation." (PMID 31475014, 2019). "Indeed, in the present study, global IL-4Rα−/− mice had impaired hepatic granuloma development alongside elevated serum IL-10 levels compared with wild-type control mice and CD4+ T cell specific IL-4Rα−/− mice." (PMID 31475014, 2019).
Granuloma (continued). "We also demonstrated that mice lacking IL-4Rα expressing B cells have enlarged liver and gut granulomas, and display a mixed cytokine profile indicated by augmented secretion of Th1, Th2, and Th17 cytokines at 24 weeks post-infection." (PMID 30619289, 2018). "Genetically resistant mice do not represent a suitable model to analyse potential IL-4Rα-dependent mechanisms because, in response to low-dose aerosol Mtb infection, wild-type and IL-4Rα mice did not develop centrally necrotizing granulomas." (PMID 24979482, 2014). "Our findings demonstrate that direct IL-4Rα signalling in a subpopulation of granuloma macrophages is not essential for MMR and Ym1 expression and these cells are restricted to the periphery of LysMcreIl4ra−/lox granulomas." (PMID 20502521, 2010). "Importantly, although previous studies have confirmed the involvement of these receptors in granulomas, our data reveal a novel aspect: the spatial expression pattern shows that activated JAK3/STAT6 signaling largely overlaps with IL4R/IL13R expression but is conspicuously excluded from giant cells." (PMID 40521183, 2025). "Indeed, IL-4Rα knockdown during chronic schistosomiasis did not lead to gut bleeding and did not affect animal viability but ameliorated liver pathology with reduced granuloma size and fibrosis in the liver and no visible scarification and reduced level of liver and spleen enlargement." (PMID 28827803, 2017).
melanoma (10 papers, 2006 to 2023). A malignant, usually aggressive tumor composed of atypical, neoplastic melanocytes. "In a transgenic mouse model with overexpression of IL4, IL4/IL4Rα suppressed the development of melanoma through activation of the P21-mediated STAT6 pathway and inhibition of anti-apoptotic BCL2 expression." (PMID 33419470, 2021). "Expression of IL-4Rα on melanoma cell lines was higher than other cancer cell lines, which was associated with higher cancer cell growth inhibition and apoptotic cell growth." (PMID 26993600, 2016). "IHC studies indicated also that IL-4R staining was localized in melanoma cells, as well as in interstitial inflammatory cells and in residual lymphoid tissue." (PMID 17129373, 2006). "The highest expression of IL-4 and IL-4Rα was found in melanoma cells among the cancer cells." (PMID 26993600, 2016). "IL-4R develop allergic reactions, modulate the function of monocytes and macrophages and has been shown over-expressed in a variety of human cancer cells in vitro and in vivo like melanoma, breast, ovarian, renal, and head and neck." (PMID 16893473, 2006). "However, direct binding between melanoma cells and platelets was not different between GPIb wild-type, GPIb-deficient, or IL4R/GPIbα-tg platelets." (PMID 35366951, 2022). "Since IL-4 and IL-4Rα were highly expressed in melanoma cells, and melanoma cell growth has been known to be significantly affected by cytokines, we chose melanoma cells for further mechanism and in vivo studies to investigate the role of IL-4 in melanoma growth." (PMID 26993600, 2016). "In this study, four MDSC subsets were analyzed in the PBMCs of advanced melanoma patients, at baseline and 12 weeks after Ipilimumab: CD14+IL-4Rα+ M-MDSCs, CD14+HLA-DRlow/− M-MDSCs, Lin−HLA-DR−CD33+CD11b+ eMDSCs, and CD15+IL4-Rα+ PMN-MDSCs." (PMID 32793228, 2020). "Our present results showed that expression of IL-4 and IL-4Rα in SK-MEL-28 and B16F10 melanoma cells were increased." (PMID 26993600, 2016).
Obesity (10 papers, 2012 to 2023). Accumulation of substantial excess body fat. "HF diet feeding augmented ex vivo IL-4 secretion by splenocytes, white adipose tissue (WAT) inflammation, and the severity of obesity-associated sequelae — the latter dependent on IL-4Rα-driven STAT6 activation." (PMID 34302121, 2021). "We next determined the impact of IL-4Rα on severity of obesity-associated metabolic sequelae." (PMID 34302121, 2021). "Interleukin-4 (IL-4) and IL-13 signaling via IL-4Rα regulates adipose tissue lipolysis, insulin sensitivity, and liver fibrosis in obesity." (PMID 34302121, 2021). "Future studies investigating tissue/cell type specific deletion of IL-4Rα in context of HF + HC diet-driven obesity, EE, and metabolic disease are warranted." (PMID 34302121, 2021). "To correlate the contribution of IL-4Rα altered inflammation to obesity we next studied the role of IL-4Rα using a well-established mouse model of HF diet-induced obesity." (PMID 34302121, 2021). "Here we demonstrate that HF + HC diet feeding augmented the occurrence of obesity-associated sequelae via engagement of non-hematopoietic IL-4Rα expression." (PMID 34302121, 2021). "Our new insights demonstrating the impact of IL-4Rα expression to high fructose-driven obesity development provide the opportunity for greater examination of IL-4 axis and the downstream linked non-canonical pathways to high-fat + high carbohydrate diets-associated metabolic disease pathogenesis." (PMID 34302121, 2021). "As the IL-4Rα is a shared receptor for IL-4 and IL-13, altered IL-13 levels in obesity might also play a role." (PMID 34302121, 2021). "Our findings highlight potential contribution of non-hematopoietic IL-4Rα activation of a non-canonical signaling pathway that regulates the HF + HC diet-driven induction of obesity and severity of obesity-associated sequelae." (PMID 34302121, 2021). "In sum, our report highlights an undervalued role for IL-4Rα signaling in the context of high fructose-driven obesity suggesting that greater examination of this signaling pathway could lead to novel insights into disease pathogenesis." (PMID 34302121, 2021). "Furthermore, IL-6 stimulates polarization and proliferation of M2 macrophages via induction of IL-4R expression as shown in mouse models of obesity." (PMID 31694340, 2019). "However, the contribution of IL-4Rα to sugar rich diet-driven obesity and metabolic sequelae remains unknown." (PMID 34302121, 2021). "Together, these findings may invoke the important role of non-hematopoietic locus of IL-4Rα expression as a modulator of HF + HC diet-driven weight gain and obesity-associated sequelae." (PMID 34302121, 2021). "Thus, it is plausible that novel pharmacological intervention in the IL-4/IL4Rα axis function, in both hematopoietic as well as non-hematopoietic cells, would provide novel approaches to dampen high dietary fructose-driven metabolic harm associated with obesity." (PMID 34302121, 2021). "Collectively, our findings demonstrate that the non-hematopoietic IL-4Rα expression is important contributor to combined HF + HC diet-driven obesity." (PMID 34302121, 2021). "Future studies fully warrant the investigation of tissue specific differences in non-hematopoietic IL-4Rα expression and their contribution to HF- and HF + HC diet-induced obesity." (PMID 34302121, 2021).
pancreatic cancer (10 papers, 2005 to 2025). "Conversely, IL4R consisting of IL4Rα and IL13Rα subunits (named type II IL4R) is highly upregulated in certain types of tumors such as breast, lung, and pancreatic cancers, which is associated with poor prognosis 11-13." (PMID 38646639, 2024). "Furthermore, overexpression of IL-13 in pancreatic cancer tissues and the high co-expression of IL-13 and IL-4Rα correlated with a higher risk of lymph node metastasis." (PMID 35409019, 2022). "In addition, the polymorphisms of IL-4R involved in the etiology of pancreatic cancer have been examined." (PMID 33804263, 2021). "Hereby these results may provide the mechanistic explanation on the molecular level of previously obtained results that demonstrated an increased risk for lymph node metastases in a human pancreatic cancer specimen with high Interleukin-4 receptor expression." (PMID 28350325, 2017). "In Panc-1 human pancreatic tumor xenografts, IL4R-Abx inhibited the tumor volumes, tumor weights, number of metastatic nodules in the lungs, and TUNEL+ apoptosis levels more effectively than Abx." (PMID 38646639, 2024). "The protein levels of IL-13Rα1, IL-4Rα and γc in cultured human pancreatic cancer cell lines A818-6, AsPC-1, Capan-1, PANC-1 and MIA PaCa-2, were determined by Western blot (WB)." (PMID 35409019, 2022). "Based on Timer2.0 analysis, we learned that SMS2 is positively correlated with IL4Rα expression in pancreatic cancer." (PMID 36324684, 2022). "IL-4 and IL-13 act on pancreatic cancer cells mainly through their receptor heterodimers IL-4-receptor-alpha (IL-4Rα) and IL-13Rα1, termed type II IL-4R, via signal pathways of STAT3/6, IRS-ERK/PI3K-Akt and mTOR." (PMID 35409019, 2022). "The differential expression of IL-4Rα and IL-13Rα1 has to be taken into account when considering a cytokine-targeted therapy in pancreatic cancer." (PMID 35409019, 2022). "All pancreatic cancer cell lines expressed IL-13Rα1 (47 kDa), IL-4Rα (140 kDa) and γc (64 kDa) at various levels." (PMID 35409019, 2022). "In our previous studies, the expression of IL-4 and IL-13 ligands, as well as IL-4Rα and IL-13Rα1 receptor chains, was shown in pancreatic cancer cell lines." (PMID 35409019, 2022). "In line with previous results for IL-4Rα, our data showed an inhibitory effect of IL-13Rα1-downregulation on cell viability/growth in two different pancreatic cancer cell lines." (PMID 35409019, 2022). "Now, increasing evidence indicates salient activities of IL-4, IL-13 and their specific receptor complex IL-4Rα/IL-13Rα1 in carcinomas including pancreatic cancer." (PMID 35409019, 2022). "The expression of IL-4 and IL-13, as well as IL-4Rα and IL-13Rα1 receptor chains, was shown in several cultured pancreatic cancer cell lines by us and by other research groups." (PMID 35409019, 2022). "While the tumour promoting role of IL-4Rα on pancreatic cancer cells in vitro and in vivo has been shown before, the role and mechanism of action of IL-13Rα in pancreatic cancer is yet unclear." (PMID 35409019, 2022). "The overexpression of IL-4R in cultured pancreatic cancer cell lines and in tumor specimens resected from pancreatic cancer patients has been determined by different research groups." (PMID 33804263, 2021). "Our group demonstrated that IL-13R and IL-4R were expressed in pancreatic cancer cell lines, such as PANC-1, MIAPaCa-2, and CAPAN-1." (PMID 33450900, 2021). "The silencing of IL4Rα inhibited the growth and invasiveness of pancreatic cancer cells by suppressing the STAT3 and Akt pathways." (PMID 33419470, 2021). "Immuno-fluorescence staining showed an increase not only in the expression of IL-4Rα in pancreatic cancer cells, but also in the M2 macrophages expressing IL-4Rα in the samples from pancreatic cancer patients compared with normal tissues." (PMID 33804263, 2021).
pancreatic cancer (continued). "Our group demonstrated the expression of IL-4Rα in pancreatic cancer cell lines ASPC-1, Capan-1, MIA PaCa-2, COLO-357, PANC-1, and T3M4 by Northern blot and Western blot (WB) analysis." (PMID 33804263, 2021). "In order to test the in vitro and in vivo influence of IL-4Rα on pancreatic cancer cells, we planned to establish clones with IL-4Rα-downregulation on protein level." (PMID 28350325, 2017). "Together with the observation that IL-4Rα-downregulated tumors exhibited lower Ki67 levels, the IL-4 receptor pathway in pancreatic cancer cells seems to stimulate cell proliferation." (PMID 28350325, 2017). "The present study aimed to address the role of IL-4Rα in growth and migrating properties of pancreatic cancer in vitro and in vivo." (PMID 28350325, 2017). "In summary, our results clearly demonstrate that signaling via IL-4Rα can induce mitogenic signaling and promote the malignant phenotype of human pancreatic cancer cells." (PMID 28350325, 2017). "The present study indicates that endogenously expressed IL-4 and IL-4Rα contribute to the malignant phenotype of pancreatic cancer cells by activating diverse pro-oncogenic signaling pathways." (PMID 28350325, 2017). "The aim of our study was to determine the role of endogenously expressed IL-4-receptor-α-chain (IL-4Rα) in pancreatic cancer cells." (PMID 28350325, 2017). "IL13Rα2 was hypothesized to be a decoy receptor for IL13Rα1 and the type II IL-4R complex, but updated evidence suggests that IL-13 may signal through IL-13Rα2 to promote pancreatic cancer cell proliferation and invasion." (PMID 33804263, 2021). "A hybrid peptide named IL-4Rα-lytic peptide could bind to IL-4Rα on pancreatic cancer cells and the lytic peptide could kill the cancer cells in vitro and in vivo." (PMID 33450900, 2021). "We detected both receptor chains participating in the type-II-IL-4-receptor (140 kDa IL-4Rα and 47 kDa IL13Rα1) in 7 different pancreatic cancer cell lines, derived from both pancreatic primaries (BxPC-3, MIAPaCa-2, PANC-1) as well as from metastases (AsPC-1, Capan-1, COLO-357, T3M4)." (PMID 28350325, 2017). "Thus, the aim of the present study was to determine the role of IL-4Rα expression in the progression of human pancreatic cancer cells." (PMID 28350325, 2017). "Pancreatic cancer cells and tissues also express high levels of IL-4Rα." (PMID 15714203, 2005). "It was also reported that several cultured pancreatic cancer cell lines express IL-4Rα." (PMID 15714203, 2005). "In addition, a hybrid peptide (IL-4Rα-lytic) containing a target moiety to bind to IL-4Rα and a cellular toxic lytic peptide that selectively kills cancer cells showed anticancer potential in pancreatic cancer cell lines expressing IL-4Rα and in a xenograft mice model of BXPC-3 cells." (PMID 33804263, 2021). "It is also possible that the expression of the IL-13Rα1 chain, which associates with the IL-4Rα chain to form a functional receptor, may influence the effects of exogenous IL-4 although MIA PaCa-2 cells as well as the other pancreatic cancer cells lines express IL-13Rα1." (PMID 15714203, 2005). "We used two pancreatic tumor models to further examine the antitumor effects of IL4R-Abx: KPC transgenic mice and Panc-1 human pancreatic tumor xenografts." (PMID 38646639, 2024). "In the pancreatic tumor tissues of KPC mice, IL4R-Abx increased the M1-macrophage population and decreased the MDSC population at higher levels than Abx, while the M2-macrophage population and CD8+ T-cell/Treg ratio were equivalent to those of Abx." (PMID 38646639, 2024). "Therefore, IL-4R might be targeted for pancreatic cancer therapy." (PMID 33804263, 2021). "Thus, it is not surprising that IL-4Rα is involved in the etiology of pancreatic cancer as a risk factor, where a variant of IL-4 (G3017T) might influence the risk of pancreatic cancer development according to the presence of allergies." (PMID 33804263, 2021).
pancreatic cancer (continued). "All tested pancreatic cancer cell lines AsPC-1, BxPC-3, Capan-1, COLO-357, MIAPaCa-2, PANC-1 and T3M4 expressed both IL-4Rα (140 kDa) and IL-13Rα1 (47 kDa) at various expression levels." (PMID 28350325, 2017). "In contrast, the endogenous activation of IL-4Rα in pancreatic cancer, either by auto- and paracrine IL-4 stimulation or by constitutive activation of IL-4Rα and its effects has not yet been examined." (PMID 28350325, 2017). "Additionally, while different pancreatic cancer cell lines showed no profound differences in migration, the reduced IL-4Rα expression lead to impaired directional as well as non-directional cell movement in our experiments." (PMID 28350325, 2017). "Interestingly, 15 of 16 (94%) specimens resected from PDAC patients exhibiting high-level co-expression of IL-13 and IL-4R had lymph node metastases, which reveals that IL-13 in conjunction with IL-4R in the pancreatic cancer cells seems to facilitate lymph node metastasis." (PMID 33804263, 2021).